PHF11 (PHD finger protein 11)
Description:
Positive regulator of Th1-type cytokine gene expression.
Synonyms: BCAP; NY-REN-34; IGER; APY; IGEL; IGHER; NYREN34
Tractability: PROTAC: ubiquitination databases record sites on it; its protein half-life has been measured.
Gene: Protein-coding gene on chromosome 13 (49,495,095 to 49,528,981, forward strand). Ensembl gene ENSG00000136147.
Subcellular location: Nucleus
Subcellular location (Human Protein Atlas): Nucleoplasm; Nuclear membrane
Gene Ontology:
Molecular function: protein binding
Cellular component: nuclear membrane; nucleoplasm; nucleus
Genetic constraint (gnomAD): Loss-of-function variants: 2 observed, 1.21 expected, observed/expected ratio (o/e) 1.65, 90% interval 0.48 to 1.93. That is too few expected variants to judge how well the gene tolerates losing a copy. Missense variants: 35 observed, 23.95 expected, observed/expected ratio (o/e) 1.46, 90% interval 1.11 to 1.87. Synonymous variants: 23 observed, 13.04 expected, observed/expected ratio (o/e) 1.76, 90% interval 1.22 to 1.96.
Homologues: Orthologues: chimpanzee PHF11 (99% identical), macaque PHF11 (94% identical), dog PHF11 (66% identical), rabbit PHF11 (64% identical), guinea pig PHF11 (63% identical), pig PHF11 (57% identical), mouse Phf11d (52% identical), rat Phf11 (52% identical), mouse Phf11c (50% identical), mouse Phf11a (46% identical), mouse Phf11b (46% identical), Drosophila melanogaster pie (12% identical), and 1 more. Paralogues in human: PHF6 (23% identical), G2E3 (18% identical), PHF7 (16% identical).
Diseases named in the same sentence as PHF11 in open-access papers:
PHF11 is named in the same sentence as 20 diseases in open-access papers, as found by Europe PMC text mining. Sharing a sentence is not in itself a finding about the gene and the disease. The quoted sentences say what the papers report.
asthma (14 papers, 2005 to 2024). "On the other hand, two genes are not involved in regulating protein complex assembly; those are GBP5, which has a role in the innate immune system and inflammation, and PHF11, which is linked to asthma." (PMID 35003208, 2021). "We have previously, through positional cloning, established that polymorphisms of PHF11 on human chromosome 13 are associated with asthma susceptibility and the asthma-related trait of total serum immunoglobulin E concentration (IgE)." (PMID 25091723, 2014). "Previously, human genetic studies have shown association between polymorphisms within the gene encoding plant homeodomain zinc finger protein 11 (PHF11) and asthma-related phenotypes." (PMID 25091723, 2014). "The association between SNPs of PHF11 and asthma or asthma-associated traits has been investigated in many subsequent studies with the majority confirming a positive association in a number of ethnic populations." (PMID 25091723, 2014). "For PHF11 and HLA-G, the associations with asthma or asthma-related phenotypes were only significant at the nominal level, and became not significant after the adjustment for multiple testing." (PMID 19951440, 2009). "It is interesting to note that an allele in the 3’ untranslated region of PHF11 that is associated with asthma and dermatitis reduces the expression of PHF11 and that this is correlated with reduced binding of the transcription factor Oct-1, which is highly expressed in epithelial cells." (PMID 26573531, 2015). "We found that DPP10 was significantly associated with bronchial hyperresponsiveness (BHR) and BHR asthma after the adjustment for multiple testing; while the associations of PHF11 with positive skin reactions to antigens and the associations of HLA-G with BHR asthma were only nominally significant." (PMID 19951440, 2009). "We have established and characterised a novel mouse mutant for Phf11 which we propose will be a useful tool for furthering our understanding of Phf11 function allowing insights into the pathogenesis of inflammatory-mediated diseases such as asthma." (PMID 25091723, 2014). "Although evidence showed that childhood and adult asthma differed in several parameters, the associations between PHF11, DPP10, HLA-G and asthma or asthma-related phenotypes were found in both groups." (PMID 19951440, 2009). "In this article, we examined the associations of polymorphisms in the identified top regions of PHF11, DPP10, and HLA-G with asthma and asthma-related phenotypes in a Chinese population, using a population-based study design." (PMID 19951440, 2009). "Associations between SNPs in PHF11, DPP10, HLA-G and asthma or asthma-related phenotypes, adjusted for age, gender, height, weight, BMI and smoking status." (PMID 19951440, 2009). "Initial functional studies by others suggested that PHF11 may have a role in the regulation of T-cell activities, although the precise functional role(s) of PHF11 in asthma pathogenesis is as yet undetermined." (PMID 25091723, 2014). "It is probably due to the small effect sizes of the genetic variants and lack of power in the current study that the associations of PHF11 and HLA-G with asthma or asthma-related phenotypes failed to reach the study-wide significance level." (PMID 19951440, 2009). "PHF11 is located on chromosome 13 and is most commonly cited as an asthma candidate gene." (PMID 19590686, 2009). "Although asthma is the complex disease with the largest number of genome scans (currently more than 15 studies), few genes have been associated with the disease (as far as we know; those are ADAM33, DPP10, PHF11, GPRA, and Vitamin D receptor)." (PMID 16115313, 2005). "Future work will need to focus on the functions of PHF11 and SETDB2 in asthma pathophysiology, in particular, how the two molecules work together during immune cell regulation." (PMID 26378653, 2015).
asthma (continued). "Six asthma candidate genes, ADAM33, NPSR1, PHF11, DPP10, HLA-G, and CYFIP2, located at different chromosome regions have been positionally cloned following the reported linkage studies." (PMID 19951440, 2009).
atopic dermatitis (4 papers, 2009 to 2023). "The G allele of the SNP rs1046295, located in the 3′-UTR of PHF11, has also been shown to be preferentially transmitted to children with atopic dermatitis as well as showing association with decreased PHF11 RNA in Th1 cells." (PMID 25091723, 2014). "Phf11 is associated with allergy atopic dermatitis in children." (PMID 37205376, 2023).
Allergy (2 papers, 2015 to 2023). An allergy is an immune response or reaction to substances that are usually not harmful. "Polymorphisms in PHF11 have been associated with dermatitis and allergy and PHF11 regulates the transcription of T-cell cytokines as well as class switching to IgE in activated B-cells." (PMID 26573531, 2015). "A role for PHF11 in IFNG gene expression, and more recently the finding that PHF11 increases class switch recombination to IgE in murine B-cells, supports a role for PHF11 in allergic disease." (PMID 26573531, 2015).
viral infection (2 papers, 2015 to 2020). "This latter notion is consistent with the apparent lack of activity in both murine and feline PHF11 proteins, despite the prevalence of FFV infections, and the additional cellular functions unrelated to viral infection that have been ascribed to human and mouse PHF11 genes." (PMID 32678836, 2020).
chronic lymphocytic leukemia (1 paper, 2022). "The deletion and methylation of PHD finger protein 11 (PHF11) were associated with chronic lymphocytic leukemia and Ewing sarcoma, respectively." (PMID 35923577, 2022).
eczema (1 paper, 2017). "Lastly, PHF11, a transcriptional activator of the Th1 effectors interleukin-2 (IL2) and interferon-γ (IFNG), is predicted to be associated to eczema." (PMID 28598986, 2017).
inflammatory skin disease (1 paper, 2015). Inflammatory skin disorders covers a broad category that includes many conditions ranging in severity, from mild itching to grave medical health complications These disorders are common in people of all ages and races. "The importance of skin barrier homeostasis in the context of inflammatory skin diseases, together with reports identifying PHF11 as an interferon-induced gene, have led us to examine its role in the innate immune response of keratinocytes." (PMID 26573531, 2015).
influenza infection (1 paper, 2019). "Similarly, the expression of PHF11 was increased after influenza infection which can confirm its role in the diminution of pro-inflammatory chemokine and increase the IFNG due to the infection." (PMID 31665046, 2019).
prostate carcinoma (1 paper, 2016). A carcinoma that arises from epithelial cells of the prostate gland. "Similarly, the genes EPSTI1 and PHF11 (also part of the 21 gene group) localize to chromosome 13 and are co-deleted in ~15% of prostate cancer patients." (PMID 27366948, 2016).
schizophrenia (1 paper, 2012). A major psychotic disorder characterized by abnormalities in the perception or expression of reality. "Five were not located in any gene, and four were located in genes (ATP8A2, LHFP, PHF11, RCBTB1, and PIBF1 (C13orf24)) not yet shown to be associated with schizophrenia." (PMID 22214315, 2012).
vitiligo (1 paper, 2021). Generalized well circumscribed patches of leukoderma that are generally distributed over symmetric body locations and is due to autoimmune destruction of melanocytes. "In total, we propose the genes NUBPL, PHF11, SETDB2, RCBTB1, PTP4A1, and at a weaker replication level the genes LITAFD, CARHSP1 and OR2C1 as possible candidates for vitiligo-like depigmentation in grey horses." (PMID 34696794, 2021).
infection (4 papers, 2011 to 2020). The state of being infected such as from the introduction of a foreign agent such as serum, vaccine, antigenic substance or organism. "Here, we demonstrate that infection of a variety of foamy viruses is inhibited by the interferon-stimulated gene product, PHF11, in a species-dependent manner." (PMID 32678836, 2020). "To elucidate which step in the FV replication cycle is inhibited by PHF11, we first determined the timing with which sensitivity to inhibition by PHF11 was lost during a single cycle of infection." (PMID 32678836, 2020). "We sought to resolve the apparent discrepancy in the effects of PHF11 on the U3-GFP reporter following infection with PFV-rRFP versus CNCR-2A-Tas." (PMID 32678836, 2020). "The overexpression of PHF11 due to the infection with Japanese encephalitis virus, avian influenza A virus, and Epstein-Barr Virus were reported previously." (PMID 31665046, 2019). "Other genes involved in immune response which were up regulated in all time point of infection were Mpa 21, Mx2, Mx1 Phf11, Tgtp, B2 m and Tap1." (PMID 21371334, 2011). "To identify the region(s) of PHF11 that determine antiviral activity, we generated chimeric human-feline PHF11 proteins that were all well expressed and challenged U3-GFP cells expressing each of the chimeric PHF11 proteins with PFV in single-cycle infection assays." (PMID 32678836, 2020). "We suggest that in addition to its role in circulating T-cells, PHF11 also plays a role in the innate immune response of keratinocytes and that a reduction in PHF11 expression may contribute to inflammation and tissue remodeling following infection or tissue damage." (PMID 26573531, 2015). "A review of the literature revealed that PHF11 is an interferon stimulated gene (ISG) and that its expression is increased following infection by several different viruses." (PMID 26573531, 2015). "Once infection is established, and Tas has been expressed, PHF11 no longer exhibits antiviral activity." (PMID 32678836, 2020). "To investigate whether this sequence divergence affected antiviral activity, we expressed the mouse (Mmd) and feline (Fc) PHF11 proteins in U3-GFP or CRFK cells and measured their effect on PFV in a single-cycle and spreading infection." (PMID 32678836, 2020). "Cells were infected with these virions at a MOI of less than 0.01 to ensure that each hygromycin-resistant colony would represent a single integration event, and we measured the number of colonies that formed following infection in the presence or absence of PHF11." (PMID 32678836, 2020). "None of the mouse PHF11 genes inhibited PFV replication, and the feline PHF11 exhibited little activity against PFV or FFVFCA infection in U3-GFP cells." (PMID 32678836, 2020).
cancer (1 paper, 2020). A tumor composed of atypical neoplastic, often pleomorphic cells that invade other tissues. "Among the top ERGs altered by deep CNAs, the majority showed amplifications, with the exception of HR, PHF11, and SETB2, which were commonly deleted in many cancer types." (PMID 32963031, 2020).
tumor (1 paper, 2021). "The highlighted genes PHF11, SETDB2, CARHSP1 and LITAFD, are associated with the innate immune system, while the genes RCBTB1, LITAFD, NUBPL, PTP4A1, play a role in tumor suppression and metastasis." (PMID 34696794, 2021).
PHF11 also shares sentences with these, for which no sentence is quoted: breast carcinoma (1 paper); dermatitis (1); Ewing sarcoma (1); lung carcinoma (1); prostate tumor (1); rheumatoid arthritis (1).